PHGDH (phosphoglycerate dehydrogenase)
Diseases named in the same sentence as PHGDH in open-access papers (continued):
Sharing a sentence is not in itself a finding about the gene and the disease.
cancer (continued). "Moreover, tumor-related protein p73 (TRP73), hypoxia-inducible factor (HIF)-1, specificity protein 1, and nuclear transcription factor Y have been reported to induce the expression of PHGDH, PSAT1, and PSPH, which contribute to regulating serine biosynthesis and metabolism in cancer cells [,61]." (PMID 37187454, 2023). "However, the anti-cancer effect of PKM2-IN-1 alone or combined with PHGDH inhibitor in NSCLC has not yet been reported." (PMID 37284309, 2023). "HKs (HK1 and HK2), PFK1 and PFK2, G6PD, pyruvate kinase, phosphoglycerate dehydrogenase (PHGDH), lactate dehydrogenase, phosphoglycerate kinase 1 (PGK1), enolase (ENO), isocitrate dehydrogenase (IDH), and glucose transferase (GLUT) serve as ideal pharmacological targets to treat cancer." (PMID 36984785, 2023). "Our study thus may broaden the use of PHGDH targeting strategies for cancer therapy, not only in PHGDH-overexpressing cancers, but also in cancer types or subtypes with PHGDH hyperactivation although PHGDH is not overexpressed." (PMID 36823188, 2023). "Moreover, these molecules demonstrated their ability to reduce the proliferation of cancer cell lines overexpressing PHGDH (SiHa, HL-60) without affecting proliferation in cell lines with little or no expression of this enzyme (MDA-MB-231, HL-60 shPHGDH)." (PMID 31979167, 2020). "Importantly, the lack of tumor formation argues that PHGDH expression alone is not sufficient to drive cancer in melanocytes." (PMID 31331318, 2019). "Although the main role identified for PHGDH so far is in contributing to serine synthesis, this might not explain why certain cancers seem to rely on PHGDH, as serine is also taken up exogenously." (PMID 29262655, 2017). "Moving forward, the challenge will be to determine whether or not cancer cells expressing elevated levels of PHGDH require additional serine for growth." (PMID 25574168, 2014). "However, for many cancer cells PHGDH expression alone could not fully explain sensitivity to serine withdrawal." (PMID 40654753, 2025). "However, the regulatory role of PHGDH in cancer has not been fully elucidated." (PMID 38710705, 2024). "Therefore, PHGDH might be a potential therapeutic target and biomarker for several cancers, a possibility that has not been investigated in BC." (PMID 32386122, 2020). "Our observations revealed that the absence of PHGDH impaired M2-like TEM polarization, regardless of the PHGDH levels in the corresponding cancer cells." (PMID 38409249, 2024). "Since the more recently developed PHGDH and SHMT inhibitors are not yet clinically applicable in humans, sertraline reflects a perfect candidate for ser/gly dependent cancers by targeting SHMT." (PMID 38160212, 2024). "The gene expression profile coincides with the metabolic alterations, hinting to a critical role of PDK4 and PHGDH in mediating the metabolic reprogramming and proliferative effects of FXR activation in cancer cell lines but not the primary hepatocytes." (PMID 26728993, 2016). "Our data revealed an increase in serine and related metabolites, along with an increased expression of serine/folate transporters in undifferentiated cancer, but there was no increase in expression of SSP-related genes, such as PHGDH, PSPH, and PSAT1, compared to differentiated cancer." (PMID 38331894, 2024).
tumor (231 papers, 1988 to 2026). "In tumor-associated macrophages (TAMs), PHGDH expression is significantly upregulated; inhibition of PHGDH disrupts cellular bioenergetics and mitochondrial respiration, suppresses mTORC1 pathway activation, and attenuates the M2 phenotype transition." (PMID 41344159, 2025). "While IR, as a standalone therapy, effectively inhibited tumor expansion and marginally increased survival, ablation of PHGDH markedly boosted tumor susceptibility to IR, leading to the most substantial increase in survival across all treatment modalities." (PMID 40102981, 2025). "In silico analysis of GBM patient data assessed SSP enrichment and PHGDH expression linked with tumor stemness." (PMID 40102981, 2025). "Genetic knockout or site-specific mutation of the PHGDH gene markedly inhibits tumor cell proliferation, underscoring its potential as a therapeutic target in cancer treatment." (PMID 41415540, 2025). "Treating RCC with a PHGDH inhibitor induces apoptosis and reduces the growth of HIF2α-deficient tumor cells." (PMID 38945960, 2024). "Tumour mediated stress signals trigger the induction of PHGDH in endothelial cells that drives a shift in central metabolism, triggering proliferation and vessel sprouting of the tumour associated endothelial cells that promote tumour growth." (PMID 38698089, 2024). "We also predicted phosphoglycerate dehydrogenase enzyme (PHGDH) gene expression levels to be causally associated with MEKi efficacy, where knockdown of this gene increased tumor sensitivity to MEKi and overexpression led to MEKi resistance." (PMID 38730673, 2024). "NOTCH1-mutated tumours did show higher expression of serine/glycine metabolism enzymes PHGDH, SHMT1 and SHMT2." (PMID 36932191, 2023). "Remarkably, during the revision of this work a study showed that PHGDH-mediated serine synthesis is altered in tumor-associated ECs24." (PMID 37880317, 2023). "Overexpression of PHGDH has been associated with higher tumor grade, shorter relapse time and decreased overall survival." (PMID 36291844, 2022). "In gliomas, PHGDH interacts with the N-terminus of FoxM1 to hinder its ubiquitination, thus causing degradation of the proteasome and promoting the proliferation of tumor cells." (PMID 35344765, 2022). "In most cases, tumor cell proliferation is promoted by increased level of PHGDH and supressed when PHGDH is knocked out or mutated in specific site." (PMID 32226297, 2020). "In PTC, PHGDH expression was associated with tumor size (p = 0.003), with an increased tumor size in PHGDH-positive cases." (PMID 27277113, 2016). "To examine the influence of PHGDH ablation on the expression of macrophage-associated markers, we used fluorescence-activated cell sorting to isolate TAMs from Phgdhfl/flCx3cr1-Cre tumor-bearing mice and analyzed the mRNA expression of several protumorigenic and proinflammatory markers." (PMID 38409249, 2024). "Serine biosynthesis from glucose via 3-carbon intermediates (i.e., 3-phosphoglycerate) has been linked to development of multiple tumor types and differential expression of PHGDH appears to represent a component of the stress response under conditions of nutrient deprivation and/or oxidative stress." (PMID 32599707, 2020). "Interestingly, by mechanisms that are yet to be defined, the elevated expression of the PHGDH orthologue in humans is associated with multiple drug resistance and associated cell re‐differentiation in tumour cells." (PMID 29575327, 2018). "However, the role of PHGDH in tumor-associated macrophages (TAMs) is poorly understood." (PMID 38409249, 2024). "In addition, most experiments examining the effects of PHGDH mutation on tumor growth have utilized mouse strains lacking adaptive immunity, and systemic administration of pharmacological drugs concurrently affects both tumor cells and the TME." (PMID 38409249, 2024). "Previous studies have suggested that PHGDH may be associated with tumor resistance." (PMID 36803157, 2023).
tumor (continued). "Critical research priorities include spatiotemporal tracking of PHGDH nuclear translocation at tumor-nerve interfaces to decode perineural invasion mechanisms, and single-cell metabolomic profiling of PHGDHhigh populations in immunosuppressive niches." (PMID 41486146, 2026). "This adaptive plasticity establishes PHGDH as a pleiotropic metabolic hub that deciphers environmental challenges through context-specific circuits, enabling tumor survival under nutrient stress." (PMID 41486146, 2026). "PHGDH promotes tumor progression through its classical metabolic functions and non-canonical signaling roles." (PMID 41486146, 2026). "Glucose restriction triggers AMPK/p38-dependent phosphorylation, inducing PHGDH nuclear translocation to sustain tumor growth under nutrient stress." (PMID 41486146, 2026). "Remarkably, either KO or inducible-KD of PHGDH markedly inhibited the self-renewal ability of GSCs, as evidenced by the result of the tumor sphere formation experiments, the diminished GSC viability, and by the results of the in vitro limiting dilution assay." (PMID 40102981, 2025). "At present, research on the nanodelivery systems utilizing passive targeting for the delivery of PHGDH inhibitors in tumor treatment remains limited, though recent studies report preliminary validation." (PMID 41415540, 2025). "Our results indicate that PHGDH is minimally expressed in normal tissues but highly expressed in tumour tissues." (PMID 40660426, 2025). "Tumors with homogeneously high PHGDH expression tend to have higher tumor staging (pT), but interestingly, lymph node staging (pN) is higher in tumors with heterogeneous or low PHGDH expression." (PMID 39973065, 2025). "Mechanistically, PKCζ, a tumor suppressor, acts upstream of PHGDH to directly repress its expression under nutrient stress." (PMID 40598535, 2025). "The final score of PHGDH immunostaining was obtained by the product of staining intensity score (0, 1 +, 2 +, and 3 +) and the percentage of positive tumor cells (0% to 100%)." (PMID 40640948, 2025). "Both combinations reduced tumor burden more effectively than monotherapy, confirming that dual targeting of PHGDH’s enzymatic and RBP functions is a viable combination strategy for HCC." (PMID 40681503, 2025). "Upregulated PHGDH in glioma TECs promoted tumor growth by production of nucleotide precursors and maintenance of redox homeostasis." (PMID 39567756, 2025). "Coherently, combining Ser and Glycine (Gly) starvation with PHGDH inhibition is much more effective in impairing tumor progression than the sole Ser or Gly limitations in in vitro and in vivo models." (PMID 40640948, 2025). "Together with the observed impact of NCT-503 on PHGDH activity in cell-based models, these findings are consistent with both tumor uptake and PHGDH inhibition in vivo." (PMID 39377369, 2025). "PHGDH-mediated serine synthesis contributes to one-carbon metabolism and generates various downstream metabolites to participate in tumor growth, tissue development or immune-related disease." (PMID 40383841, 2025). "PHGDH overexpression induces resistance to erlotinib in tumor xenograft mouse models, whereas treatment with the PHGDH inhibitor NCT-503 effectively restores erlotinib sensitivity in vitro and in vivo." (PMID 41415540, 2025). "Next-generation PHGDH inhibitors have shown greater potency and selectivity for PHGDH and, in combination with dietary depletion of serine and glycine, have yielded a more dramatic reduction in tumor growth." (PMID 39377369, 2025). "Confirming previous evidence, heterogeneous PHGDH expression reflects a significant variability in PHGDH levels in 3D organoids and tumor samples derived from CRC patients." (PMID 40640948, 2025).
tumor (continued). "Our analysis highlighted a significant positive correlation between the tumor stemness score and both the PHGDH mRNA level (R = 0.43) and the enrichment score of the serine metabolic pathway (R = 0.2)." (PMID 40102981, 2025). "Using in vivo tumor-bearing genetically engineered and xenograft mouse models, pharmacological inhibition of PHGDH increased survival, implicating the de novo serine/glycine synthesis pathway as a pro-survival mechanism sustaining tumor progression." (PMID 39377369, 2025). "In the present study, we underscored a heterogeneous expression of PHGDH among CRC patients and we confirmed high PHGDH levels in organoids and tumor tissue specimens from patients less responsive to 5-FU-based therapy." (PMID 40640948, 2025). "The results demonstrated that PHGDH knockdown significantly inhibited PDX tumor growth, reduced PRKCD mRNA and protein levels and decreased the expression of mitophagy-related molecules." (PMID 40681503, 2025). "This difference hints at distinct regulatory mechanisms for PHGDH expression in tumour cells versus GCs." (PMID 40660426, 2025). "The results showed that PSAT1 and PSPH were consistently upregulated in tumour tissues in five GEO datasets, while PHGDH, SLC1A4 and SLC38A5 were upregulated in four datasets." (PMID 40660426, 2025). "Our bioinformatic analysis revealed a marked reduction in PHGDH expression in tumor tissues, which shows a strong positive correlation with PFKP expression." (PMID 41333208, 2025). "This complexity stems from the fact that PHGDH has both tumor-promoting and potential anti-metastatic effects." (PMID 40265021, 2025). "Conversely, the knockdown of PHGDH inhibits tumor growth and sensitizes cells to ferroptosis, which makes targeting PHGDH therapeutically relevant." (PMID 40076506, 2025). "The findings revealed that suppression of PHGDH robustly inhibited tumor proliferation in the GBM models and notably increased survival rates." (PMID 40102981, 2025). "Due to the importance of serine synthesis and metabolism in endothelial cell dynamics, pharmacological inhibition of PHGDH using NCT503 or WQ2201 abrogated tumor vessel sprouting and enhanced sensitization to CAR-T therapy in glioblastoma." (PMID 39567756, 2025). "PHGDH overexpression is linked to the TNM stage and tumor size and independently predicts a poor prognosis in CRC patients." (PMID 40989165, 2025). "Recent study advancements have underscored the function of PRMT1 in augmenting the activity of PHGDH via methylation, thereby facilitating serine production and demonstrating tumor‐promoting effects on HCC in both in vitro and in vivo studies." (PMID 41256732, 2025). "Overexpression of PHGDH has been observed in NSCLC and is associated with enhanced tumor growth and poor prognosis." (PMID 40469185, 2025). "In cervical cancer cells, PHGDH knockout downregulates Bcl-2 expression while upregulating cleaved caspase-3 levels in vitro, thereby promoting tumor cell apoptosis in vivo." (PMID 41415540, 2025). "In vivo co-IF staining for PHGDH and 8-OHdG in GSC-derived xenografts and human GBM specimens revealed lower 8-OHdG levels in high PHGDH-expressing tumor cells, indicating PHGDH’s protective effect against oxidative DNA damage." (PMID 40102981, 2025). "Tumor cells enhance serine metabolism by upregulating the phosphoglycerate dehydrogenase (PHGDH)-mediated de novo synthesis pathway and activating exogenous transport systems." (PMID 41415540, 2025). "PHGDH, the rate-limiting enzyme in this pathway, is overexpressed and drives tumor proliferation, invasion, and therapeutic resistance in various malignancies." (PMID 41415540, 2025). "A study involving 319 NSCLC patients demonstrated significantly increased PHGDH expression at both mRNA and protein levels in tumour tissues compared to adjacent non-tumour tissues." (PMID 41154605, 2025).
tumor (continued). "Considering the elevated expression of PHGDH, SLC1A5 and SLC38A2 in CRC and their association with tumour proliferation, metastasis and patient prognosis, we selected these genes for validation in real‐world patient cohorts." (PMID 40660426, 2025). "Novel PHGDH inhibitors have shown efficacy in preclinical models, reducing tumor growth and enhancing sensitivity to chemotherapy." (PMID 40469185, 2025). "Currently, research on active targeting-based nanodelivery of PHGDH inhibitors for tumor treatment remains limited." (PMID 41415540, 2025). "This study confirmed that changes in the PHGDH expression level and serine metabolism were observed predominantly in tumor endothelial cells." (PMID 38945960, 2024). "Modifications of the amino acid residues of PHGDH are crucial for its ability to control tumor progression." (PMID 38945960, 2024). "ASS1 knockout and knockdown resulted in increased serine synthesis as well as tumor growth through stabilization of PHGDH protein levels, and this effect was significantly abrogated by PHGDH knockout." (PMID 38710705, 2024). "In acute myeloid leukemia, genetic or pharmacological blockade of PHGDH suppresses tumor development and increases the sensitivity to chemotherapy." (PMID 38115544, 2024). "For example, targeting enzymes in the tumor protein pathways (e.g. phosphoglycerate dehydrogenase, PHGDH) is an effective method to avoid sorafenib resistance." (PMID 39759148, 2024). "Our in vivo data confirmed that the serum αKG levels in PHGDH conditional knockout mice were considerably decreased upon tumor injection." (PMID 38409249, 2024). "As the rate-limiting enzyme, tumor cells highly express PHGDH to counteract limited serine availability." (PMID 38218942, 2024). "In conclusion, our study provides novel insights into the role of PHGDH-mediated serine biosynthesis in shaping the behavior of TAMs and their crosstalk with tumor cells." (PMID 38409249, 2024). "Previous studies have reported that NCT503, a small molecule PHGDH inhibitor, impairs the synthesis of glucose‐derived serine and induces apoptosis in BC, thereby suppressing tumor growth." (PMID 38874588, 2024). "In the serine-restricted TME, tumor cells can regulate the expression of phosphoglycerate dehydrogenase, allowing more 3-phosphoglycerate to enter the serine synthesis pathway." (PMID 38384814, 2024). "Depletion of PHGDH in macrophages led to reduced tumor growth, altered TAM polarization toward an antitumor phenotype, and improved antitumor T-cell immunity." (PMID 38409249, 2024). "To exclude the possibility of off-target effects of the Cx3cr1-Cre strain on the status of PHGDH in T cells, we evaluated PHGDH protein expression in T cells within tumor tissues via immunofluorescence staining of CD3." (PMID 38409249, 2024). "This shows that the level of PHGDH activity has a significant impact on tumor cell migration and CRC metastasis." (PMID 38945960, 2024). "PHGDH also interacts with the translation initiation factors eIF4E and eIF4A1 to promote translation initiation in the cytoplasm, thereby accelerating tumour development." (PMID 38577610, 2024). "By incubating tumor cells with a Ser/Gly-free medium, we observed increased PHGDH protein levels likely as an adaptative response to Ser starvation." (PMID 39706853, 2024). "These include a number of PHGDH inhibitors, which are effective in limiting tumour growth in various preclinical models." (PMID 38698089, 2024). "Here, we found that the T helper 2 (Th2) cytokine interleukin-4 and tumor-conditioned media upregulate the expression of PHGDH in macrophages and promote immunosuppressive M2 macrophage activation and proliferation." (PMID 38409249, 2024). "Conversely, RNF5, an E3 ubiquitin ligase, mediates PHGDH degradation and suppresses tumor progression." (PMID 38218942, 2024). "Inhibitors of PHGDH, such as NCT-503 and CBR-5884, have been shown to suppress cell proliferation and tumor development by targeting PHGDH." (PMID 38710705, 2024).